MMP8 (matrix metallopeptidase 8)
Description:
Can degrade fibrillar type I, II, and III collagens.
Synonyms: MMP-8; PMNL-CL; CLG1; HNC
Tractability: Small molecule: an approved drug acts on it; a structure with a bound ligand is known; a high-quality ligand is known; it belongs to a druggable protein family. Antibody: UniProt places it where antibodies can reach, with high confidence; its Gene Ontology location is reachable by antibodies, with high confidence; UniProt predicts a signal peptide or a membrane-spanning region. PROTAC: a small molecule that binds it is known.
Target class: Metallo protease; Metallo protease M10A subfamily; Metallo protease MAM clan; Protease; Enzyme
Chemical probes: ML034
Gene: Protein-coding gene on chromosome 11 (102,711,796 to 102,727,050, reverse strand). Ensembl gene ENSG00000118113.
Subcellular location: Cytoplasmic granule; Secreted, extracellular space, extracellular matrix
Subcellular location (Human Protein Atlas): Vesicles; Predicted to be secreted
Pathways (Reactome):
Extracellular matrix organization: Activation of Matrix Metalloproteinases; Collagen degradation; Degradation of the extracellular matrix
Immune System: Neutrophil degranulation
Gene Ontology:
Molecular function: endopeptidase activity; peptidase activity; serine-type endopeptidase activity; tumor necrosis factor binding; metalloendopeptidase activity; zinc ion binding; metallopeptidase activity
Biological process: endodermal cell differentiation; positive regulation of tumor necrosis factor production; proteolysis; cellular response to lipopolysaccharide; collagen catabolic process; extracellular matrix disassembly; extracellular matrix organization; positive regulation of microglial cell activation; positive regulation of neuroinflammatory response; positive regulation of tumor necrosis factor-mediated signaling pathway
Cellular component: extracellular matrix; extracellular region; specific granule lumen; tertiary granule lumen
Genetic constraint (gnomAD): Loss-of-function variants: 57 observed, 48.55 expected, observed/expected ratio (o/e) 1.17, 90% interval 0.95 to 1.46. The upper end of that interval is the gene's LOEUF score, 1.46, which puts it in group 6 of 6, group 1 being the genes least tolerant of losing a copy. Missense variants: 630 observed, 543.89 expected, observed/expected ratio (o/e) 1.16, 90% interval 1.08 to 1.24. Synonymous variants: 221 observed, 188.68 expected, observed/expected ratio (o/e) 1.17, 90% interval 1.05 to 1.31.
Homologues: Orthologues: chimpanzee MMP8 (99% identical), macaque MMP8 (92% identical), dog MMP8 (78% identical), pig MMP8 (76% identical), mouse Mmp8 (73% identical), rat Mmp8 (72% identical), guinea pig MMP8 (72% identical), rabbit MMP8 (59% identical), Drosophila melanogaster Mmp1 (33% identical), Caenorhabditis elegans zmp-3 (28% identical), Caenorhabditis elegans zmp-4 (24% identical), Caenorhabditis elegans zmp-1 (23% identical), and 4 more. Paralogues in human: MMP1 (57% identical), MMP3 (52% identical), MMP10 (51% identical), MMP13 (49% identical), MMP27 (48% identical), MMP12 (47% identical), MMP20 (45% identical), MMP2 (40% identical), MMP16 (39% identical), MMP15 (39% identical), MMP24 (39% identical), MMP14 (37% identical), and 11 more.
Diseases named in the same sentence as MMP8 in open-access papers:
MMP8 is named in the same sentence as 356 diseases in open-access papers, as found by Europe PMC text mining. Sharing a sentence is not in itself a finding about the gene and the disease. The quoted sentences say what the papers report.
periodontitis (290 papers, 2012 to 2026). An acute or chronic inflammatory process that affects the tissues that surround and support the teeth. "In our systematic meta-analysis, we investigated the potential association between salivary MMP-8 and aMMP-8 levels and periodontitis by examining a total of 35 relevant studies." (PMID 40045958, 2025). "This meta-analysis investigates the association between salivary MMP-8 and aMMP-8 levels and periodontitis." (PMID 40045958, 2025). "The current meta-analysis provides compelling evidence of the association between salivary MMP-8/aMMP-8 levels and periodontitis." (PMID 40045958, 2025). "This allele has been previously implicated in periodontitis and peri-implant tissue destruction due to its upregulation of neutrophil-derived MMP-8, which is critical in degrading type I collagen and initiating inflammatory cascades." (PMID 40423054, 2025). "Salivary MMP-8 and aMMP-8 levels are significantly associated with periodontitis, highlighting their potential as diagnostic biomarkers." (PMID 40045958, 2025). "According to recent meta-analyses, MMP-8 and aMMP-8 are useful diagnostic biomarkers for both periodontitis and gingivitis." (PMID 41002732, 2025). "MMPs, particularly MMP-8, play a crucial role in periodontitis and are closely associated with periodontal status." (PMID 39554809, 2024). "Several diagnostic kits for periodontitis and peri-implantitis based on MMP-8 have been commercialized." (PMID 39554809, 2024). "Among extensively studied salivary biomarkers, the combination of MMP-8 and IL-6 has shown the highest diagnostic accuracy for periodontitis." (PMID 39554809, 2024). "The role of polymorphisms in MMP-8 genes in association with periodontitis has also been demonstrated; however, this will be presented in later sections of this paper." (PMID 38473967, 2024). "Some work has also addressed the link between MMP-8 polymorphisms and the risk of periodontitis, but this topic is currently poorly studied and contradictory." (PMID 38473967, 2024). "Again, however, a single study indicates that a higher frequency of MMP-8+17C/G is associated with a higher incidence of periodontitis." (PMID 38473967, 2024). "In the current study, the diagnostic precision of salivary MMP-8 and IL-1β as indicators of gingivitis and periodontitis was evaluated." (PMID 38086426, 2024). "Elevated MMP-8 concentrations have been associated with e.g., cardiovascular diseases and periodontitis." (PMID 39917664, 2024). "Due to the function of MMP8 in tissue degradation, an increased concentration represents a risk factor for the development of periodontitis." (PMID 39597886, 2024). "Especially elevated levels of active MMP-8 (aMMP-8) based on local analyses have emerged as diagnostic enzymes for inflammatory states such as periodontitis, peri-implantitis and type II diabetes." (PMID 37249720, 2024). "In patients with periodontitis, there is a progressive loss of attachment correlated with salivary MMP-8 levels." (PMID 38535833, 2024). "Variations in the MMP8 gene that have been mostly investigated in association with periodontitis are MMP8 −799 C > T (rs11225395) +17 C/G (rs2155052) and −381A/G (rs11225395)." (PMID 37371608, 2023). "GCF levels of MMP-8 in early pregnancy are elevated in women with severe periodontitis and linked to the development of GDM." (PMID 37342498, 2023). "Proanthocyanin, a potent grape seed antioxidant, has been reported to reduce inflammation and alveolar bone loss due to periodontitis by decreasing HIF-1α and MMP-8 levels and increasing osteoblast activity in diabetic rats periodontitis." (PMID 37501927, 2023). "We performed a search using keywords MMPs, metalloproteinase, MMP-8, MMP8, MMP8 polymorphism, oral health, periodontitis, peri-implantitis, periimplantitis, implant loss, caries." (PMID 37371608, 2023).
periodontitis (continued). "The results of the two meta-analyses published lead to similar conclusions suggesting that the variant T allele of MMP8 −799 C > T SNP is associated with an increased risk of periodontitis in four genetic models." (PMID 37371608, 2023). "Elevated activated MMP‐8 (aMMP‐8) associate with periodontitis and a diagnostic point‐of‐care technology has been developed based on aMMP‐8." (PMID 37877535, 2023). "Other authors showed that periodontitis and diabetes have been associated with COVID-19 poor outcomes and both these diseases have been correlated with elevated MMP-8 levels, further highlighting the role of MMPs as key players in COVID-19 risk and escalation." (PMID 36523781, 2022). "IFMA has a high affinity for the active MMP‐8 which is the molecular form associated with the onset and progression of periodontitis." (PMID 35304757, 2022). "Several studies have reported significant increases in MMP-8 levels in subjects with chronic periodontitis and periodontitis associated with diabetes." (PMID 35163727, 2022). "The T allele is associated with enhanced expression of MMP‐8 and lower risk of generalized aggressive periodontitis, and the TT genotype significantly associated with an increase in serum MMP‐8 concentrations." (PMID 35315933, 2022). "This case control study examined the associations of HLA antigens and periodontitis with the salivary level of active MMP‐8 (aMMP‐8)." (PMID 34448550, 2021). "ROC curves presented a high diagnostic accuracy for the discrimination of healthy from periodontitis sites in the (a) MMP-8 crude (AUC = 0.90, 95% CI 0.83–0.96) and adjusted models (AUC = 0.90, 95% CI 0.83–0.96)." (PMID 34441437, 2021). "Pathologically elevated levels of matrix metalloproteinase-8 (MMP-8) and Lactoferrin in oral fluids have been associated with the presence of gingivitis/periodontitis." (PMID 34353321, 2021). "MMP-8 is a major mediator of tissue destruction in periodontitis, and a correlation between increased MMP-8 activity and progressive loss of connective tissue attachment and osteolysis has been demonstrated through numerous clinical studies." (PMID 34067332, 2021). "In that study, IL-1β, MMP-8, and Pg were calculated together to obtain a cumulative risk score that was highly correlated with advanced periodontitis." (PMID 34001101, 2021). "This is the first study on the associations of HLA types with the salivary level of active MMP‐8 in periodontitis." (PMID 34448550, 2021). "In keeping with previous results, also in the current study, the salivary level of active MMP‐8 was clearly associated with periodontitis and its grade." (PMID 34448550, 2021). "The downregulation of miR-1226 expression in periodontitis patients was correlated with the increased probing pocket depth, attachment loss, plaque index, bleeding index, and MMP-8 levels." (PMID 34592963, 2021). "The progression of periodontitis is usually controlled by the degree of inflammation which can be measured by inflammatory biomarkers, such as MMP-8 which is worthy investigated as both diagnostic aid and therapeutic target in periodontitis." (PMID 33952216, 2021). "Concerning the identification of mild to severe periodontitis sites, the (t) MMP-8-adjusted model demonstrated a high diagnostic precision, defined by ROC curves with AUC ≥ 0.80 (AUC = 0.81, 95% CI 0.72–0.92)." (PMID 34441437, 2021). "Uncontrolled diabetes is related to increased risk of periodontitis, and it predisposes to accelerated periodontal destruction reflected in oral fluids as increased MMP-8 and -9 activation." (PMID 34054959, 2021). "Diabetes has been shown to act as a bidirectional risk factor for periodontitis and oral diseases due to the prolonged inflammatory state induced by up-regulated inflammatory mediators such as MMP-8, leading to increased periodontal tissue destruction." (PMID 33916950, 2021).
periodontitis (continued). "In fact, the active MMP-8 type was predominant in periodontitis, whereas the latent forms were mainly associated with gingivitis in some studies." (PMID 34441437, 2021). "Regarding the local impact of periodontitis, previous research has shown that decreased levels of IL-4 and increased levels of MMP-8, PGE2 and S100A12 in the oral cavity are associated with higher periodontal deterioration." (PMID 34501547, 2021). "This can be supported in part by an animal study, where knockout MMP8 mice with induced periodontitis showed increased alveolar bone loss in relation to uninfected mice." (PMID 33255937, 2020). "The excessive secretion of MMP-8 and -9 leads to the degradation of collagen in the soft tissue and the alveolar bone and are associated with tissue destruction during periodontitis." (PMID 33391628, 2020). "According to a recent systematic review, aMMP-8/MMP-8 is currently the most accurate diagnostic biomarker in GCF for periodontitis in systemically healthy patients." (PMID 31979091, 2020). "A study conducted on Finnish adolescents showed that an active MMP8 PoC test can effectively detect initial periodontitis associated with single nucleotide polymorphisms of VDR and MMP3 genes." (PMID 33081038, 2020). "In saliva, aMMP-8/MMP-8 is also among the best five biomarkers, and the combination of aMMP-8/MMP-8 and IL-6 seems the most promising salivary diagnostic marker for periodontitis." (PMID 31979091, 2020). "The high concentration of MMP-8 has been linked to the severity of inflammation in clinical studies and was associated with an aggressive form of periodontitis." (PMID 33391628, 2020). "Hyp is associated with both gingivitis and periodontitis, where it is associated with activated neutrophil matrix metallopeptidase 8 (MMP8)." (PMID 32329896, 2020). "Beneficial effects of adjunctive SDD therapy is likely to be related to the reduced levels of two major periodontitis-associated MMPs, MMP-8 and -9, and their potential oxidative activator MPO." (PMID 30669541, 2019). "Neutrophil collagenase, also known as matrix metalloproteinase-8 (MMP-8), has been identified as a major collagenolytic enzyme that causes active periodontal tissue destruction in periodontitis and peri-implantitis." (PMID 30360358, 2018). "Among the MMPs family, the active form of MMP-8 (aMMP-8) in GCF is the most prominent collagenase (collagenase 2) associated with periodontitis." (PMID 29587716, 2018). "In clinical dentistry, however, elevated salivary MMP-8 levels have been proposed to be diagnostic for periodontitis, but large-scale validation studies are needed." (PMID 29163477, 2017). "Previous investigations showed that salivary MMP-8 levels are associated with progressive loss of attachment in periodontitis." (PMID 28117682, 2017). "Our results provided some evidence to support an elevated risk between periodontitis susceptibility and MMP-3-1171 A5 allele and MMP-8-799 T allele, and a reduced risk between periodontitis susceptibility and MMP-9-1562 T allele." (PMID 27095260, 2016). "Variation in MMP-8 gene, particularly of −799 C/T, −381 A/G, and +17 C/G SNPs, has been investigated in association with periodontitis." (PMID 27194818, 2016). "Smoking and periodontitis were both associated with increased levels of MMP8 and MMP9 in gingival crevicular fluid in the sense of additional factors." (PMID 26656474, 2015). "It has been demonstrated that GCF levels of MPO and MMP-8 and associations between them were related to development and treatment responses in patients with chronic periodontitis." (PMID 26132583, 2015). "In support of this, an association between active MMP-8 and myeloperoxidase has recently been reported during chronic periodontitis progression." (PMID 22436166, 2012). "Consequently, salivary MMP-8 detection can be a valuable diagnostic indicator for the presence and progression of periodontitis." (PMID 41149323, 2025).
periodontitis (continued). "MMP-8 serves as an informative biomarker reflecting the degree of periodontal inflammation; its determination is essential in early, subclinical diagnosis of periodontitis for preventive treatment and prevention of tooth loss." (PMID 40363983, 2025). "Importantly, our study demonstrates that ISM1 and MMP-8 levels in GCF reflect the severity of periodontitis, as evidenced by their strong positive association with clinical parameters such as PD and CAL." (PMID 41063065, 2025). "A high concentration of MMP-8 in gingival crevicular fluid is linked to the severity of periodontitis, possibly decreasing after periodontal treatment, although maintaining considerable levels during persistent periodontitis." (PMID 38474009, 2024). "Importantly, IL-6 and MMP-8 results validated the biological separation of groups associated with the clinical progression of periodontitis, supporting proteomic findings and offering additional protein-level evidence." (PMID 38802345, 2024). "The objective, diagnostic value of BOB and MMP-8 testing from subclinical symptoms to severe periodontitis may offer a new perspective in the early detection of periodontitis." (PMID 39336968, 2024). "Immunohistochemical results of the present study revealed that the presence of Td-dentilisin in CP-gingival tissues was increasingly associated with the increase in MMP-8 immunoexpression along with an increase in clinical stage and grade disease severity of periodontitis." (PMID 38786309, 2024). "Periodontitis-related gradual loss of attachment is correlated with salivary MMP-8 levels." (PMID 38535279, 2024). "Furthermore, compared to healthy controls, salivary levels of MMP-8 and IL-1 are substantially linked to severe periodontitis." (PMID 38535833, 2024). "In particular, the RANKL/OPG ratio and MMP-8 levels, which are directly associated with alveolar bone resorption and soft tissue degradation, respectively, were maintained below those detected during previous periodontitis." (PMID 36902236, 2023). "Assessing MMP-8 is an extremely valuable tool for diagnosing and targeting this enzyme could be an efficient approach for treating periodontitis or early implant loss." (PMID 37371608, 2023). "Avellan reported that the local application of capsaicin to the alveolar mucosa could cause a significant elevation and activation of MMP-8, an essential destructive protease in periodontitis." (PMID 35911651, 2022). "Salivary S100A8, S100A12, and MMP‐8 concentrations were associated with periodontitis, ABL, the number of periodontal pockets with PPD 4 to 5 mm, and especially the number of periodontal pockets with PPD ≥ 6 mm (OR for 10‐fold increase in S100A8: 4.22; 95% CI, 2.15 to 8.30; P < 0.001)." (PMID 35315933, 2022). "We investigated whether the polymorphisms linked to serum MMP‐8 associate with periodontitis, periodontal parameters, and saliva concentrations of TCC, S100A8, and S100A12 in a well‐characterized, relatively large sample of middle‐aged or elderly participants." (PMID 35315933, 2022). "As MMP‐8 is a central mediator of tissue destruction in periodontitis, genetic polymorphisms that affect its gene expression or its release from the cells might affect the individual's susceptibility to periodontal disease." (PMID 35315933, 2022). "We could hypothesize that both under‐ and overexpression of MMP‐8 may increase the risk of periodontitis, but further studies on the link between periodontitis and rs11225395 are needed for any stronger conclusions." (PMID 35315933, 2022). "Also, molecular forms of neutrophilic and mesenchymal‐type MMP‐8 such as 20–27 kDa fragments were shown to be elevated in periodontitis, suggesting a potential role as early diagnostic markers of active periodontal disease." (PMID 35304757, 2022).